EGFR (epidermal growth factor receptor)
Diseases named in the same sentence as EGFR in open-access papers (continued):
Sharing a sentence is not in itself a finding about the gene and the disease.
tumor (continued). "The tumor microenvironment can also induce tumor cell metastasis via secretion of cyclooxygenase-2 (COX2) and epidermal growth factor receptor (EGFR), the factors responsible for the organophilic nature of tumor cell metastasis." (PMID 36338717, 2022). "Cinobufotalin also blocks the growth and metastasis of the tumor by down-regulating the expression of vascular endothelial growth factor (VEGF) and epidermal growth factor receptor (EGFR)." (PMID 35814224, 2022). "Literature also suggests that genes or signaling pathways regulating cell proliferation may be associated with accelerated tumor progression and a poor prognosis; notable examples include the Notch pathway, hypoxia-inducible factor 1-alpha (HIF1-α), and epidermal growth factor receptor (EGFR)." (PMID 36299463, 2022). "The EGFR has been reported to be expressed in a small proportion of UM cell lines and tumours, and the ligand EGF has been reported to activate the phosphorylation of EGFR and its downstream mediator AKT in EGFR-expressing cell lines." (PMID 35781872, 2022). "LAMC2, a target gene of miR-134, activates the EGFR/MAPK pathway but is also downregulated by miR-134, thereby inhibiting the migration and invasion of OSCC tumour stem cells by suppressing the PI3K-Akt signalling pathway." (PMID 35327656, 2022). "EGFR and VEGFR2 play the important role in various tumors, leading to the growth and proliferation of tumor cells." (PMID 36139078, 2022). "In this study, we show for the first time that a single, EGFR‐TPMIL construct encapsulating a lipidated BPD molecule and irinotecan chemotherapy, is capable of simultaneously controlling tumor growth, remediating desmoplasia, and doubling survival." (PMID 35748165, 2022). "The stimulation of the EGFR activates the RAS–RAF–MEK–ERK signaling pathway, which promotes tumor cell proliferation." (PMID 36005935, 2022). "The transcription factor GABP is a central node in this pathway, receiving signals from EGFR through AMPK and selectively activating TERT expression, the rate limiting factor in telomerase activity and tumor cell immortality." (PMID 36130485, 2022). "Analysis of CyCIF data revealed a strong positive correlation between EGFR and CD73 expression at a single cell level in tumor cells." (PMID 35973991, 2022). "An experiment demonstrated that cetuximab (IgG1 monoclonal antibody against EGFR) and bevacizumab (IgG1 monoclonal antibody against VEGF) alone or in combination inhibited tumor cell growth and angiogenesis in in vivo models of ATC." (PMID 36612173, 2022). "Although both patients had very good tumor response after EGFR-TKI therapy and post-operative N0 disease, the limited number of patients with tumor invasion to mediastinum or chest wall precludes a definitive conclusion." (PMID 36581631, 2022). "Although A549 contain wild‐type EGFR, knockdown of BMI1 still blocked spheroid and tumour formations." (PMID 35794816, 2022). "This patient was enrolled in the same neoadjuvant osimertinib clinical trial and also showed a minimal EGFR TKI response, with 68.3% tumor cell viability in the osimertinib-treated, resected tumor specimen upon clinical pathology assessment." (PMID 35579943, 2022). "During anti-EGFR therapy in CRC patients, CAF promotes tumor resistance to EGFR by secreting growth factors, such as FGF1, FGF2, HGF, TGF-β1 and TGF-β2." (PMID 35740594, 2022). "When metformin is used in combination with anti-tumor drugs, such as traditional chemotherapy drugs, epidermal growth factor receptor tyrosine kinase inhibitors (EGFR-TKI), or immune checkpoint inhibitors (ICIs), it improves the anti-tumor effects of the drug." (PMID 35222283, 2022). "Examples of palmitoylated proteins include tubulin and EGFR, as well as RAS-family GTPases that require palmitoylation to promote tumor formation activity." (PMID 36578540, 2022).
tumor (continued). "There were a trend or significant differences in PD‐L1 expression between different histological types in NSCLC, different EGFR and ALK status, and different tumor tissue storage time." (PMID 34841687, 2022). "Basic studies have found that dual intervention with EGFR and HER2 can deplete tumour initiating cells, optimising chemotherapy management, and preventing the progression of desmoplastic resistant PCa cells." (PMID 36330452, 2022). "Our study showed that the anti-EGFR mAb-EV-Ver-A can effectively target GBM and inhibit the tumor growth with minimal toxicity." (PMID 35052809, 2022). "The combination of THZ1 and EGFR-targeted CAR-T cells exhibit a better ability to inhibit immune resistance and prevent tumor proliferation and metastasis processes compared to applying to CAR-T cells alone in TNBC tumor models." (PMID 35935930, 2022). "Epidermal growth factor receptor (EGFR) is frequently involved in the pathogenesis and progression of tumor and represents an important pharmacological target in cancer therapy." (PMID 35955669, 2022). "Upon EGFR CAR T cell treatment, the tumor cells displayed an upregulation of the adhesion molecule CD54 that was unseen in control-treated tumors." (PMID 35836798, 2022). "We next evaluated roles for MERTK, EGFR, and AXL in NSCLC tumor cell expansion, migration, and colony formation using siRNA-mediated knockdown." (PMID 35708914, 2022). "One novel mechanism of this triple combination in reducing the tumor burden of H1975 xenografts was the effect on serum exosome production and PDL1 and EGFR expressions." (PMID 35745729, 2022). "As a whole, these results showed that accumulation of ATG6‐L1 β inhibits gefitinib‐induced apoptosis in cells with acquired resistance to EGFR‐TKI and promotes tumor growth." (PMID 35593080, 2022). "PI3K/AKT/mTOR, MAPK, PLCγ, and JAK/STAT are the four major representative downstream signaling pathways activated by EGFR or HER family members, which are related with tumorigenesis, tumor growth, and progression." (PMID 36254250, 2022). "EGFR is frequently overexpressed in TNBC and known to promote tumor growth and metastasis, however, the role of EGFR in CSC clusters and polyclonal metastasis is yet to be clarified." (PMID 35725558, 2022). "In tumor cells, upregulated CIRS-7 exerts its sponge effect by targeting miR-7 and upregulates its key target genes, including EGFR, CCNE1, and PIK3CD, to induce tumor cell proliferation." (PMID 36139427, 2022). "MCLA-158 showed antitumor activity against RAS mutated and wt CRC patient-derived organoids in vitro and induced either tumor regression or stasis in esophageal squamous and gastric adenocarcinoma patient-derived xenograft models expressing LGR5 and EGFR." (PMID 36185288, 2022). "The commercial formula also enhanced the anticancer effects of radiotherapy by decreasing lung metastasis and EGFR expression and increasing apoptosis in LLC1 tumor-bearing mice." (PMID 36547898, 2022). "Therefore, each generation of EGFR‐TKIs might elicit a different resistant tumor phenotype." (PMID 35029047, 2022). "In addition to the association between the timing of LM occurrence and patient outcome, we attempted to explore the correlation between the radiological severity of LM, CSF tumor cell counts, and EGFR detection sensitivity, which could provide meaningful information in clinical practice." (PMID 35740489, 2022). "Transforming growth factor alpha (TGFα) is a natural ligand for epidermal growth factor receptor (EGFR), a receptor highly expressed in tumor cells." (PMID 36297535, 2022). "Further analysis of patients with newly diagnosed EGFR-mutant advanced NSCLC showed improved PFS and OS in the tumor resection group." (PMID 36581631, 2022). "Morphine (an opioid)-induced phosphorylation of the epidermal growth factor receptor (EGFR) occurs via MOR in NSCLC cell lines, facilitating tumor proliferation and invasion." (PMID 35603146, 2022).
tumor (continued). "The RAS, EGFR, and PI3K/AKT pathways are involved in this process of modulating tumor radiosensitivity." (PMID 35200568, 2022). "Patients were divided into EGFR R, RGFR L, VEGF R and VEGF L groups based on the location of the primary tumour and the use of the first-line target therapy." (PMID 35372058, 2022). "EGFR signaling pathways have been shown to regulate a series of important events, such as cell proliferation, angiogenesis, EMT, and tumor metastasis in CRC." (PMID 36005485, 2022). "In vivo, EGFR inhibitor erlotinib increased therapeutic response to [177Lu]Lu-PP-F11N and median survival of A431/CCKBR-tumor bearing nude mice." (PMID 36045419, 2022). "OP also downregulates several epidermal growth factor receptor (EGFR)-mediated pathways, such as the JAK/STAT, PI3K/Akt, and MAPK pathways, involved in cancer cell proliferation, metastasis, and tumor vascularization." (PMID 35326525, 2022). "In the subgroup analysis of the EGFR wild type population, the presence of GAS5 SNP rs145204276 Ins/Del + Del/Del was correlated to an advanced tumor stage (p = 0.014) and distal metastases (p = 0.020) in non-smokers." (PMID 36011604, 2022). "This one patient was subjected to EGFR-TKI (erlotinib) after failed definitive chemotherapy and radiotherapy and responded with stable disease for 5 years, at which point the tumor started to regrow." (PMID 36434641, 2022). "Interestingly, detection of KRAS tumours’ mutational status is predictive as a negative marker and the patient is unlikely to benefit from EGFR antibody therapy (cetuximab, bevacizumab and panitumumab), so that patients with KRAS wild-type status seem to respond better to anti-EGFR treatment." (PMID 35326950, 2022). "Thereafter, antigen-activated and -nonactivated CAR T cells displayed distinct accumulation kinetics: while in the EGFR CAR T cell (± IL-2)-treated cohorts, the first signal emerged at the tumor site, BDCA-2 CAR T cells (± IL-2) primarily homed to the spleen." (PMID 35836798, 2022). "The combination of anti-EGFR-mAB and siRNA targeting KRAS effectively suppressed KRAS protein expression in CRC cell lines, and reduced tumor volume and tumor weight effectively in a mouse implantation tumor model with cetuximab resistance mutation." (PMID 35953863, 2022). "In this study, we investigated the anti-tumor efficacy of Nrf2 inhibitor, brusatol in combination with dual HER2/EGFR inhibitor, lapatinib and explored its potential mechanism of action as a new therapeutic regimen for HER2-positive cancers." (PMID 36090218, 2022). "Although tumor microenvironment (TME) restriction on immune cells has been well studied and significant efforts have been taken to explore the potential way to enhance T cell infiltration into the tumor bed, the mechanism of EGFR-mutation inducing un-inflamed TME remains unknown." (PMID 36482371, 2022). "Indeed, the inhibition of EGFR in cancer patients leads to skin toxicity, whose severity has shown to be positively correlated with patients’ survival and hence could be a surrogate marker of tumor response to EGFRIs." (PMID 36358726, 2022). "Overexpression of hsa_circ_0005379 expression can inhibit the expression levels of EGFR and phosphorylated EGFR, thus regulating the proliferation of OSCC tumor cells." (PMID 36483049, 2022). "In contrast, reovirus tumor-selectivity largely stems from activation of the epidermal growth factor receptor (EGFR)/Ras pathway in host cells, which has also shown to be activated in tumor-derived fibroblasts." (PMID 35869278, 2022). "Nevertheless, in NSCLC tumors carrying wild-type EGFR and ALK genes, the brain-seeding metastatic cells acquire additional genetic alterations during the early stages of tumor evolution." (PMID 36561283, 2022).
tumor (continued). "In a syngeneic mouse cancer model, EGFR TKI suppressed the glycosylation of PD-L1 and sensitized the tumor to anti-PD-1 therapy." (PMID 36443704, 2022). "TIP30 is a tumor suppressor that negatively regulates both PI3K/AKT and RAS/MAPK pathways in NSCLC and prevents EGFR nuclear translocation from inhibiting nEGFR-mediated c-myc transcription." (PMID 36115852, 2022). "Some tumors had molecular aberrations in frequently altered genes in NSCLC such as ALK, EGFR, KRAS or ROS1, as determined with the TruSight Tumor 170 sequencing panel in-house." (PMID 35329826, 2022). "Together, these in vivo results suggest that using combination therapies that include an EGFR-TKI alongside an agent to inhibit ACh/M3R signaling can decrease the establishment of residual tumors and retards tumor relapse." (PMID 36048538, 2022). "The complex blocked EGF‐mediated activation of EGFR and inhibited tumours more efficiently than when the drug was used alone, whereas the binding between VHH and EGFR endowed the tumour selectivity of the conjugate." (PMID 35593206, 2022). "GW-2974 is a highly potent tyrosine kinase receptor that inhibits EGFR and ERBB-2 in tumor cells with selectivity for tumor cells over normal cells." (PMID 36476719, 2022). "Previous studies have reported the correlation between DJ-1 and the transition of stem cells or tumor-initiating cancer stem cells (CSC), and DJ-1 induces and maintains CSC states by protecting EGFR degradation." (PMID 36202793, 2022). "To do so, we characterized cell and organelle volumes and shapes of epithelial cells in situ within EGFR+ and KRAS+ types across three stages of tumor progression, and compare them to normal AT2 cells." (PMID 36201559, 2022). "siRNA loaded PILPs resulted in a significant down-regulation of EGFR and TERT expression paralleled by a reduction of tumor growth in a xenograft mouse model of HCC." (PMID 36297407, 2022). "Compared to patients without EGFR-mutation, female, nonsmokers, tumor size<3cm, subsolid density, air bronchogram, air space, spiculation, pleural retraction, vascular convergence sign, and multiple pulmonary metastases were more common in those with EGFR-mutation (all p <0.05)." (PMID 36059655, 2022). "Inhibiting the epidermal growth factor receptor (EGFR) and vascular endothelial growth factor (VEGF)-A signaling using specific antibodies also improved the anti-tumor effect in TNBC." (PMID 36012284, 2022). "Activity in terms of reduction of tumor volumes was noted to be significantly enhanced in patients with molecular alterations in the drug targets (RET, VEGFR, EGFR, and PI3K/mTOR), supporting further development of the combination." (PMID 34551970, 2022). "Circular RNA ciRS-7 acted as a sponge of miR-7, upregulating several oncogenes (mTOR, EGFR, PIK3CD) to promote the progression of cancers in which high ciRS-7 expression correlated with worse prognosis and miR-7 acted as tumor suppressor." (PMID 35550610, 2022). "On the other hand, EGFR inhibitor can significantly down-regulate the expression of FGD5-AS1, which makes the combination of EGFR inhibitor and 5-FU show better anti-tumor effect." (PMID 35475392, 2022). "In particular, EGFR-TKIs increase the presentation of MHC class I and II molecules and potentiate T-cell-mediated tumor killing." (PMID 35742933, 2022). "The experimental data found in literature to characterize EGFR+ LUAD tumor growth are either obtained from in vitro spheroids, or from xenografted mice, reporting either tumor radius or tumor volume." (PMID 35796890, 2022). "To verify the synergistic oncogenicity occurring in ALV-J and REV co-infected tumor-bearing chickens, we established a tumor model induced by ALV-J and REV and measured the key molecules and the NF-κB/KIAA1199/EGFR pathway in three type tumors." (PMID 36291177, 2022). "Lastly, for tumor sample #8-T, although a high ratio of HX103(+) was observed, the percentage values for EGFR(+)HX103(+) and EGFR(+) were both low." (PMID 36376325, 2022).
tumor (continued). "The most widely utilized syngeneic mouse tumor model, CT26, possesses contrary data on its EGFR expression level, varying from undetectable to very high." (PMID 36432639, 2022). "Genomic landscape studies indicate that EGFR/K-RAS/MAPK pathway activation is a major impetus driving TNBC malignancy, early tumor relapse, local invasion, and metastatic spread." (PMID 36176751, 2022). "Monoclonal antibodies can either target the receptors overexpressed on tumor cells (such as HER2, EGFR, VEGFR, etc.)or target their ligands to neutralize those receptors on the cell surface (such as bevacizumab for VEGF)." (PMID 35326556, 2022). "In this PDX model, high expressions of EGFR and HER2 were observed after IHC staining tumor of GemHCl treated groups." (PMID 36550419, 2022). "Our findings corroborate EGFR expression and activity patterns observed in several TMZ-resistant cell lines and GBM patient tumor tissues." (PMID 36316307, 2022). "OPB-51602 resensitizes patients who develop resistance to EGFR TKI, resulting in tumor regression and profound metabolic responses." (PMID 36612059, 2022). "In this study, we identified Toll‐7 as a proto‐oncogene that promotes tumour growth and invasion through Egr‐JNK and EGFR‐Ras signalling." (PMID 35050535, 2022). "EGFR-targeted NB–IR700DX conjugates are selective and were able to induce selective cancer cell death in vivo in an orthotopic tumor model." (PMID 35213974, 2022). "Some targeted drugs, such as anti-angiogenesis or anti-vascular drugs and anti-epidermal growth factor receptor drugs, have also been proven to improve the efficacy of PDT further and significantly improve tumor growth control after PDT." (PMID 36466825, 2022). "C-A-Au NPs incorporating GFT-miR125b preferably accumulated at the tumor area in the Lewis lung carcinoma (LLC) xenograft tumor model and inhibited EGFR signaling, leading to tumor growth inhibition." (PMID 35954481, 2022). "Stimulation with EGF or GAS6 enhanced downstream signaling in parental EGFRMT cells, and EGFR and MERTK shared common signaling pathways that promote tumor cell survival and proliferation, including PI3K/AKT and MAPK/ERK pathways." (PMID 35708914, 2022). "Studies have found that inhibiting mutant K-RAS can reduce tumor growth and render NSCLC patients sensitive to EGFR inhibitors." (PMID 35840984, 2022). "G-protein-coupled receptors (GPCRs), integrins, folate receptors, transferrin receptors, epidermal growth factor receptor (EGFR), fibroblast growth factors (FGFRs), and sigma receptors are all used to target medicines to tumour tissues and microenvironments." (PMID 36688039, 2022). "Collectively, these data suggest that hCAP18/LL-37 promotes HCC cells proliferation through stimulation of the EGFR/HER2/Akt signals and appears to suppress the antitumor activity of 1,25(OH)2D3 in HCC xenograft tumor." (PMID 35039485, 2022). "Although about 77.4% of specimens were from the same clinical samples for both cobas EGFR test and NGS test, there is still concern of treatment-induced modification of tumor characteristics." (PMID 35945330, 2022). "Rap1 regulates integrins and cadherins by stimulating EGFR and Src/FAK, which plays essential roles in cell adhesion to ECM and cell–cell adhesion; both are crucial for tumor cell invasion and metastasis." (PMID 35322101, 2022). "In corticotroph tumor cells, these highly active USP8 mutants rescue epidermal growth factor receptor (EGFR) from ligand-induced ubiquitination and lysosomal degradation and potentiate its signaling resulting in enhanced ACTH synthesis." (PMID 35852754, 2022). "Moreover, in triple-negative BC cell lines (MDA-MB-231, MDA-MB-468, and HCC-1806), a crosstalk between LEP and IGF-1 signaling has been demonstrated to promote the transactivation of the epidermal growth factor receptor (EGFR), which may enhance tumor cell invasion and migration." (PMID 36291602, 2022).